DCBLD1 (discoidin, CUB and LCCL domain containing 1)
Synonyms: MGC46341; dJ94G16.1
Tractability: Antibody: UniProt predicts a signal peptide or a membrane-spanning region; its Gene Ontology location is reachable by antibodies, with medium confidence. PROTAC: ubiquitination databases record sites on it.
Gene: Protein-coding gene on chromosome 6 (117,453,817 to 117,569,858, forward strand). Ensembl gene ENSG00000164465.
Subcellular location: Membrane
Subcellular location (Human Protein Atlas): Cytosol
Gene Ontology:
Molecular function: signaling receptor activity
Cellular component: plasma membrane; membrane
Genetic constraint (gnomAD): Loss-of-function variants: 50 observed, 67.16 expected, observed/expected ratio (o/e) 0.74, 90% interval 0.59 to 0.94. The upper end of that interval is the gene's LOEUF score, 0.94, which puts it in group 4 of 6, group 1 being the genes least tolerant of losing a copy. Missense variants: 869 observed, 900.64 expected, observed/expected ratio (o/e) 0.96, 90% interval 0.91 to 1.02. Synonymous variants: 372 observed, 359.55 expected, observed/expected ratio (o/e) 1.03, 90% interval 0.95 to 1.13.
Homologues: Orthologues: chimpanzee DCBLD1 (99% identical), macaque DCBLD1 (97% identical), pig DCBLD1 (82% identical), rabbit DCBLD1 (80% identical), dog DCBLD1 (74% identical), guinea pig DCBLD1 (57% identical), rat Dcbld1 (55% identical), mouse Dcbld1 (55% identical), zebrafish dcbld1 (41% identical). Paralogues in human: RS1 (10% identical).
Diseases named in the same sentence as DCBLD1 in open-access papers:
DCBLD1 is named in the same sentence as 25 diseases in open-access papers, as found by Europe PMC text mining. Sharing a sentence is not in itself a finding about the gene and the disease. The quoted sentences say what the papers report.
cervical cancer (9 papers, 2024 to 2026). A primary or metastatic malignant neoplasm involving the cervix. "Recent study has implicated DCBLD1 in cancer progression, demonstrating its role in cervical cancer through lactylation-driven modulation of the pentose phosphate pathway." (PMID 41522352, 2026). "We also clarified the underlying mechanism for the elevated expression of DCBLD1 in cervical cancer at the transcriptional and post-transcriptional levels." (PMID 38291438, 2024). "Subsequently, we explored the mechanisms underlying the elevated expression of DCBLD1 in cervical cancer." (PMID 38291438, 2024). "Collectively, these findings suggest that DCBLD1 promotes cervical cancer cell proliferation, migration, and invasion in vivo and in vitro." (PMID 38291438, 2024). "Schematic illustration of DCBLD1-induced G6PD-mediated reprogramming of PPP metabolism in promoting cervical cancer progression." (PMID 38291438, 2024). "In summary, this study revealed the role of DCBLD1 in promoting the malignant progression of cervical cancer by activating G6PD-mediated PPP in vivo and in vitro." (PMID 38291438, 2024). "Consistently, the Gene Expression Omnibus (GEO) (GSE39001 and GSE75132) database was used to further validate DCBLD1 expression, which was highly expressed in cervical cancer compared to paired normal tissues." (PMID 38291438, 2024). "Consistently, the protein expression of DCBLD1 was significantly higher in cervical cancer cells than in normal cervical epithelial cells." (PMID 38291438, 2024). "In vitro and in vivo studies were conducted to investigate the impact of DCBLD1 on the progression of cervical cancer." (PMID 38291438, 2024). "In cervical cancer, the lactylation of DCBLD1 stabilizes its conformation and inhibits the degradation of G6PD, which in turn upregulates the pentose phosphate pathway within tumors and promotes cervical cancer progression." (PMID 39590360, 2024). "Normal cervical cell and cervical cancer cells were used to detect the expression of DCBLD1, we found that DCBLD1 mRNA expression was significantly higher in HeLa cells compared to HcerEpic cells." (PMID 38291438, 2024). "Overexpression of DCBLD1 is associated with poor prognosis in head and neck squamous cell carcinoma, non-small cell lung cancer, breast cancer, pancreatic cancer, and renal cell carcinoma, its specific role in the development of cervical cancer remains unclear." (PMID 38291438, 2024). "We identified G6PD-mediated oxiPPP as a crucial proliferative-related target of DCBLD1, establishing a link between DCBLD1 and the altered oxiPPP in cervical cancer." (PMID 38291438, 2024). "In human cervical cancer tissues and xenograft tumor samples, DCBLD1 positively correlated with G6PD." (PMID 38291438, 2024). "Another study indicated that L-lactic acid increases lactylation modification of the DCBLD1 protein, directly stabilizing DCBLD1 and enhancing its transcription and expression, ultimately boosting cervical cancer cell growth, invasion, and treatment resistance." (PMID 41561760, 2025). "Discoidin, CUB, and LCCL domain-containing type I (DCBLD1) is identified as an oncogene involved in multiple regulation of tumor progression, but specific mechanisms remain unclear in cervical cancer." (PMID 38291438, 2024). "To investigate whether DCBLD1 is involved in the progression of cervical cancer, we first analyzed the expression of DCBLD1 through The Cancer Genome Atlas (TCGA) database, and the results showed that patients with high DCBLD1 expression have shorter survival." (PMID 38291438, 2024). "To determine whether DCBLD1 had a direct influence on cervical cancer cell phenotypes, we firstly evaluated the proliferation of HeLa and C33A cells following DCBLD1 knockdown, achieved through the use of short hairpin RNA (shRNA)." (PMID 38291438, 2024). "Furthermore, we investigated DCBLD1 overexpression activating pentose phosphate pathway (PPP) to promote the progression of cervical cancer." (PMID 38291438, 2024).
cervical cancer (continued). "However, whether DCBLD1 triggers PPP activation to promote the proliferation of cervical cancer cells remains unclear." (PMID 38291438, 2024). "In cervical cancer, discoidin, CUB and LCCL domain-containing 1 (DCBLD1) K172la inhibits ubiquitination, enhancing the stability and extending the protein half-life." (PMID 40994548, 2025). "In cervical cancer, elevated lactate levels in tumor tissues promote HIF-1α enrichment at the DCBLD1 promoter region, augmenting DCBLD1 mRNA expression." (PMID 40994548, 2025). "In cervical cancer, L-lactate not only increases the expression of Discoidin, CUB, and LCCL domain-containing type I (DCBLD1) via HIF-1α but also directly mediates DCBLD1 lactylation." (PMID 40421024, 2025). "We found that lactate increased DCBLD1 expression, activating the PPP to facilitate the proliferation and metastasis of cervical cancer cells." (PMID 38291438, 2024). "DCBLD1 overexpression inhibited G6PD autophagic degradation, activating PPP to promote cervical cancer progression." (PMID 38291438, 2024). "Furthermore, a recent study on cervical cancer found that lactate induces lactylation of discoidin, CUB, and LCCL domain-containing protein 1 (DCBLD1) at the K172 site." (PMID 40584966, 2025). "This modification stabilizes DCBLD1 expression, leading to an increase in the expression and enzymatic activity of glucose-6-phosphate dehydrogenase (G6PD), which stimulates the PPP and promotes the progression of cervical cancer." (PMID 40584966, 2025). "DCBLD1 expression was examined in human cervical cancer cells and adjacent non-tumorous tissues using quantitative reverse transcription-polymerase chain reaction, western blotting, and immunohistochemistry." (PMID 38291438, 2024).
lung carcinoma (7 papers, 2019 to 2026). "Building upon our previous identification of DCBLD1 as a lung cancer susceptibility gene, this study revealed that DCBLD1 actively participates in LUAD tumorigenesis rather than merely serving as a genetic susceptibility marker." (PMID 41522352, 2026). "Second, tumors induced in DCBLD1 KO mice using urethane established a loss-of-function paradigm, confirming the inhibitory effect of DCBLD1 deficiency on lung cancer initiation." (PMID 41522352, 2026). "Previous studies also showed the associations of the DCBLD1 expression with lung cancer and breast cancer." (PMID 35844572, 2022). "We performed LD analysis on SNP rs9387478 discovered by GWAS in search for functional variants, and found that SNP rs17079281, located in the DCBLD1 promoter, was associated with lung cancer." (PMID 32231272, 2020). "In summary, in search for functional SNPs in high LD with SNP rs9387478 identified by lung cancer GWAS, we found that SNP rs17079281, located in the promoter region of DCBLD1, was associated with lung cancer risk." (PMID 32231272, 2020). "A novel SNP rs17079281 in the DCBLD1 promoter was identified to be associated with lung cancer risk in Chinese populations." (PMID 32231272, 2020). "Linkage disequilibrium (LD) analysis, meta-analysis involving 4403 cases and 5336 controls, and two additional case–control studies have discovered a novel SNP, rs17079281, in the DCBLD1 promoter, which is associated with lung cancer risk in Chinese populations." (PMID 34208629, 2021). "In addition, lower expression of DCBLD1 was associated with less cell proliferation, suggesting a role of oncogene in lung cancer development." (PMID 32231272, 2020). "First, organoids derived from EGFRL858R/+ spontaneous lung cancer mouse-derived AT2 demonstrated a gain-of-function effect of DCBLD1 overexpression in promoting LUAD progression." (PMID 41522352, 2026). "Our study indicated that upregulation of DCBLD1 expression promoted lung cancer cell proliferation and downregulation of DCBLD1 diminished these effects in vitro." (PMID 32231272, 2020). "SNP rs17079281 C>T variation created a site for YY1 binding which repressed the DCBLD1 expression, reducing its oncogenic effect on lung cancer development." (PMID 32231272, 2020). "We demonstrated that DCBLD1 promoted lung cancer cell proliferation by influencing cell cycle progression." (PMID 32231272, 2020). "In non-smoking women, a susceptible locus for lung cancer in the DCBLD1 gene was noted, suggesting the tumorigenic potential of DCBLD1 for the first time." (PMID 35844572, 2022). "To test whether the SNP could modulate DCBLD1 expression, we measured DCBLD1 mRNA expression in cancer tissue from lung cancer patients using quantitative PCR." (PMID 32231272, 2020). "In addition, significantly higher DCBLD1 expression was found in lung cancer compared with adjacent normal tissue in a dataset available from TCGA." (PMID 32231272, 2020). "However, few studies have explored the biological function of DCBLD1 in lung cancer." (PMID 32231272, 2020).
lung adenocarcinoma (5 papers, 2019 to 2024). A carcinoma that arises from the lung and is characterized by the presence of malignant glandular epithelial cells. "Thus, the YY1 transcription repressor has a higher binding affinity for the T allele of rs17079281, which results in suppression of DCBLD1 proto-oncogene expression and, consequently, in a decreased lung adenocarcinoma risk." (PMID 34208629, 2021). "DCBLD1 has been associated with lung adenocarcinoma and glioma." (PMID 31878157, 2019). "There were 6 genes with a causal relationship to lung adenocarcinoma, including FUBP1, CTD-2012J19.3, CTD-2012J19.1, DCBLD1, NRG1 and SECISBP2L." (PMID 38834983, 2024). "To examine the effects of DCBLD1 on lung adenocarcinoma cell behaviors, we established stable cells with knockdown or overexpression of DCBLD1." (PMID 32231272, 2020). "Recently, rs6942067, a single nucleotide polymorphism (SNP) located upstream of the DCBLD1 gene, was found associated with non-smoking lung adenocarcinoma." (PMID 31878157, 2019). "In the never-smoking lung adenocarcinoma study, the DCBLD1 susceptibility locus was associated with EGFR mutations in exons 19 and 21 (in the tyrosine kinase encoding region)." (PMID 31878157, 2019). "We found that patients with homozygous T/T genotype or heterozygous C/T genotype had lower DCBLD1 expression than those with C/C genotype in lung adenocarcinoma, but not in lung squamous cell carcinoma." (PMID 32231272, 2020).
breast carcinoma (3 papers, 2017 to 2022). "Basal-like and HER2-enriched breast cancers had significantly higher DCBLD1 expression compared to the normal-like and luminal subtypes in the METABRIC cohort." (PMID 34140574, 2021). "In this study, we showed that DCBLD1 gene expression is prognostic of overall survival in NSCLC and breast cancer." (PMID 34140574, 2021).
head and neck squamous cell carcinoma (3 papers, 2021 to 2022). A squamous cell carcinoma that arises from any of the following anatomic sites: lip and oral cavity, nasal cavity, paranasal sinuses, pharynx, larynx, and salivary glands. "In head and neck squamous cell carcinoma, DCBLD1 is overexpressed, associated with poor patient prognosis." (PMID 35844572, 2022).
head and neck cancer (2 papers, 2021 to 2022). A primary or metastatic malignant neoplasm affecting the head and neck. "Given that germline SNPs in DCBLD1 are associated with non-smoking lung and head and neck cancers, and demonstrate prognostic value in other cancers, further studies are needed to evaluate its potential as a therapeutic target." (PMID 34140574, 2021). "DCBLD1 mRNA expression was significantly higher in 502 head and neck cancer patients than those in 44 non-cancer subjects (p < 0.001) and was also higher in 43 tumor tissue paired with pericarcinous tissue (p < 0.001)." (PMID 35844572, 2022). "Germline single nucleotide polymorphisms in the promoter region of the DCBLD1 gene are associated with non-smoking cases of both non-small cell lung carcinoma (NSCLC) and human papillomavirus-negative head and neck cancer." (PMID 34140574, 2021).
colorectal adenocarcinoma (1 paper, 2021). The most common type of colorectal carcinoma. "NSCLC, invasive breast carcinoma, colorectal adenocarcinoma and prostate adenocarcinoma were each represented by two cohorts for the analysis of DCBLD1 gene expression and cancer outcome." (PMID 34140574, 2021). "DCBLD1 gene expression was investigated in paired tumor tissue and normal adjacent tissue in the NSCLC (n = 108), invasive breast carcinoma (n = 111), colorectal adenocarcinoma (n = 32) and prostate adenocarcinoma (n = 52) TCGA cohorts." (PMID 34140574, 2021). "This multicenter retrospective study was designed to evaluate the prognostic value and function of DCBLD1 in the four main solid cancers: NSCLC, invasive breast carcinoma, colorectal adenocarcinoma and prostate adenocarcinoma." (PMID 34140574, 2021). "Statistically significant higher DCBLD1 in tumor tissue was observed for all four cancers with median of 1.47 fold for NSCLC, 1.54 fold for invasive breast carcinoma, 1.39 fold for colorectal adenocarcinoma and 1.25 fold for prostate adenocarcinoma." (PMID 34140574, 2021).
colorectal cancer (1 paper, 2017). A primary or metastatic malignant neoplasm that affects the colon or rectum. "In these, 8 SNPs were annotated to the same gene in pairs of height- and colorectal cancer risk-associated SNPs, leading to the following four gene annotations: BMP2, PITX1, DCBLD1, and BARX1." (PMID 28117334, 2017).
emphysema (1 paper, 2018). "For emphysema, we identified novel associations of LILRA3 and DCBLD1 using whole blood and lung tissue, respectively, and validated these findings in additional gene expression datasets." (PMID 29566699, 2018). "LILRA3, DCBLD1, and ITGA1 are at loci not previously associated with COPD or emphysema." (PMID 29566699, 2018). "We implicated genes that are genetically regulated in known COPD-susceptibility loci, such as FAM13A, and also found genes in regions that were not previously reported: WNT3 for severe COPD, and DCBLD1 and LILRA3 for quantitative emphysema." (PMID 29566699, 2018).
invasive breast carcinoma (1 paper, 2021). A carcinoma that infiltrates the breast parenchyma. "Age and stage were not reproducibly associated with DCBLD1 gene expression for invasive breast carcinoma." (PMID 34140574, 2021). "DCBLD1 gene expression was associated with a worse overall survival in multivariate analyses for both NSCLC cohorts (TCGA: P = 0.03 and GSE81089: P = 0.04) and both invasive breast carcinoma cohorts (TCGA: P = 0.02 and METABRIC: P < 0.001)." (PMID 34140574, 2021). "Patients with high DCBLD1 expression had strong upregulation of the integrin signaling pathway in comparison to patients with low DCBLD1 expression for both NSCLC and invasive breast cancer." (PMID 34140574, 2021). "For this study, 37 common genes were differentially regulated between patients of high and low DCBLD1 expression for NSCLC, invasive breast carcinoma and HNSCC." (PMID 34140574, 2021). "For NSCLC, invasive breast carcinoma and HNSCC, the upregulation of all these proteins in conjunction with high DCBLD1 expression strongly suggests that DCBLD1 is involved in focal adhesions and therefore, cell migration." (PMID 34140574, 2021). "In three cancers (NSCLC, invasive breast carcinoma and HNSCC) for which DCBLD1 had prognostic value, high DCBLD1 expression showed statistically significant upregulation of the integrin signaling pathway." (PMID 34140574, 2021). "The prognostic value of measured DCBLD1 protein levels in NSCLC, invasive breast carcinoma and HNSCC will warrant further studies." (PMID 34140574, 2021). "Patients with high DCBLD1 expression showed an upregulation of the integrin signaling pathway in comparison to those with low DCBLD1 expression in the TCGA NSCLC cohort (FDR = 5.16 × 10–14) and TCGA invasive breast carcinoma cohort (FDR = 1.94 × 10–05)." (PMID 34140574, 2021).
juvenile myelomonocytic leukemia (1 paper, 2024). A myelodysplastic/myeloproliferative neoplasm of childhood that is characterized by proliferation principally of the granulocytic and monocytic lineages. "Moreover, DCBLD1 interacts with KRAS, which is a key diagnostic and prognostic gene associated with various hematological tumors such as juvenile myelomonocytic leukemia." (PMID 38752789, 2024).
pancreatic cancer (1 paper, 2025). "Although the underlying mechanisms remain to be fully elucidated in pancreatic cancer models, research has proved that ApoE, DCBLD1 and XRCC1 are significant factors in pancreatic cancer." (PMID 41007358, 2025).
Stroke (1 paper, 2015). Sudden impairment of blood flow to a part of the brain due to occlusion or rupture of an artery to the brain. "In Chr 6q21–22, SNPs near AIM1–ATG5 are associated with stroke (P = 9.2 × 10-6) and plasma VLDL concentration (P = 4.7× 10-7), those near DCBLD1 are associated with carotid artery disease (P = 7.4 × 10-8), and a SNP in SLC35F1 is associated with heart rate (P = 4.0 × 10-10)." (PMID 25689165, 2015).